MUC1 (mucin 1, cell surface associated)
Diseases named in the same sentence as MUC1 in open-access papers (continued):
Sharing a sentence is not in itself a finding about the gene and the disease.
prostate carcinoma (continued). "One study has, furthermore, suggested that MUC-1 expression may predict prostate cancer recurrence after prostatectomy, although these results have been challenged by others." (PMID 17726465, 2007). "In the experiment, the sensor detects the MUC1 expression patterns of different prostate cancer cell line models and normal prostate cells, and is able to distinguish between normal prostate cells and different types of prostate cancer cell in clinical testing." (PMID 34770415, 2021). "Furthermore, we observed an important role of NF-κB/p65 that may involve in the inhibitory effects of solamargine on MUC1 expression and growth of prostate cancer cells." (PMID 27830724, 2016). "Furthermore, our results unveiled an additive effect of combination of solamargine and metformin in the inhibition of p65, MUC1 and prostate cancer cell growth, implying the potential new role and molecular mechanism in combination of solamargine and metformin in controlling CRPC cell growth." (PMID 27830724, 2016). "Therefore, MUC1 might have an important role in prostate cancer progression, and has been considered as a potential therapeutic target in advanced disease." (PMID 27846218, 2016). "Furthermore, the MUC1 intracellular domain has become the focus of therapeutic strategies, and MUC1 peptide antagonists have yielded promising results as anti-tumor therapies in mouse models of breast and prostate cancer." (PMID 22586492, 2012). "The finding described in this report of a prostate cancer-associated functionally relevant variation supports the notion that the MUC1 gene may be a useful marker for prostate and other cancers." (PMID 19578514, 2008). "Since MUC1 is primarily expressed in epithelial cells, common cancers of the urinary system, such as bladder cancer (BCa), renal cell carcinoma (RCC), and prostate cancer (PCa), all originate from epithelial cells." (PMID 39491020, 2024). "There are, however, several potential O-glycosylation sites in the molecule of PSA (also PAP and MUC1)-bearing sLex glycans as confirmed by ELISA and RT-PCR of the transcript levels of GCNT1 transferase in prostate cancer cells." (PMID 39594740, 2024). "Many prostate cancer clinical trials have focused on mucin-1 (MUC-1), a single pass membrane protein, for which both the expression level of MUC-1 and its glycosylation were frequently altered." (PMID 34359624, 2021). "A recent study has shown that Mucin 1 (MUC1), a transmembrane glycoprotein, was found to promote androgen independence and self-renewal of prostate cancer cells." (PMID 34298815, 2021). "We found that depending on age of prostate cancer patients and Gleason score EMT genes with distinctly altered expression are: KRT18, KRT19, MUC1 and COL4A1, CTNNB1, SNAI2, ZEB1 and MMP3." (PMID 29206234, 2017). "Subcutaneous treatments with MVA-MUC1-IL-2 were well tolerated in patients with advanced RCC, prostate cancer, or NSCLC and were shown to induce MUC1 specific responses in some of the patients." (PMID 28116088, 2017). "Prostate carcinoma cells were significantly more sensitive to CTL-mediated lysis targeting CEA (P = 0.002), brachyury (P = 0.0004), MUC1 (P < 0.0001), or PSA (P = 0.0011)." (PMID 26862729, 2016). "MUC1 exon 2 (3506G/A) genotype frequencies in blood DNA samples only demonstrated significant differences when BPH and hereditary prostate cancer samples were compared." (PMID 19578514, 2008). "After adjusting for tumour extent and Gleason score, the effect of MUC-1 was even stronger (HR 5.1 (95%CI=1.4–18) and 4.5 (95%CI=1.3–15), respectively), indicating that MUC-1 predicts prostate cancer death independently of clinical parameters." (PMID 17726465, 2007). "Moreover, overexpression of MUC1 in cancer cells hyperactivates both Erk1/2 and PI3K pathways, contributing to drug resistance in MUC1-overexpressing prostate cancer cells." (PMID 38540735, 2024).
prostate carcinoma (continued). "Mucin 1 (MUC1) is another intriguing target antigen that is overexpressed in various primary malignancies, including lung, gastric, breast, ovarian, colon, pancreatic, and prostate cancer." (PMID 35762299, 2022). "Mucin 1 (MUC1) is one of the transmembrane mucins, with a heavily glycosylated extracellular domain that extends up to 200–500 nm from the cell surface, highly expressed in malignant cancers such as breast, ovarian, lung, pancreatic and prostate cancers." (PMID 29261171, 2017). "Treatment of MUC1-positive prostate cancer cells with GO-201 lead to reduced cell proliferation and necrotic cell death, whereas no such effect was observed in MUC1-negative prostate cancer cells." (PMID 35389164, 2022). "Prostatic adenocarcinoma is very common in Iraq, it has been widely distributed among the middle and old age group since the normal and abnormal prostatic tissue expresses different MUC1 epitopes, but MUC1 epitopes specific to prostate cancer have not been well characterized." (PMID 35646176, 2022). "Indeed, in preclinical models of pancreatic and prostate cancer, CAR T cells directed against mucin-1 (MUC1) and prostate stem cell antigen (PSCA) were unable to eradicate solid tumors, and tumor escape was attributed to tumor cells expressing low densities of target antigen." (PMID 32357417, 2020). "The upregulation of SLeX has been detected on PSA, Mucin 1 (MUC1), and prostatic acid phosphatase (PAP) proteins in a panel of 10 malignant tissues (relative to matched normal tissue), opening up a new avenue for the development of prostate cancer-specific glycoprotein biomarkers." (PMID 30893936, 2019). "To determine whether MUC1 from PC3 cells carries poly-N-acetyllactosamine on its O-glycans, we first excluded N-glycans from prostate cancer cells by treatment with tunicamycin, an N-glycosylation inhibitor, and then analyzed the cell lysates by immunoprecipitation using LEL." (PMID 23165940, 2013). "The MUC1 production patterns were precisely determined in benign (RWPE-1) and prostate cancer cells (LNCaP and PC3), with no significant interference from ascorbic and uric acids, vascular endothelial growth factor, BSA, and prostate specific antigen." (PMID 33499136, 2021). "The same profile of activation of the adaptive immune response was seen in the prostate cancer patients: predominantly, CD4 T-cell responses were seen with CD8+ responses being variable, while no MUC1-reactive antibodies were induced." (PMID 29784646, 2018).
colorectal cancer (75 papers, 2007 to 2026). A primary or metastatic malignant neoplasm that affects the colon or rectum. "MUC1 which is associated with high mucin-related colorectal cancer has been shown to activate TAK1 expression in colorectal cancer, driving NFκB towards inflammation-associated cancer progression." (PMID 39068768, 2024). "Tumor-associated antigen mucin 1 (MUC1) is highly expressed in colorectal cancer and is positively correlated with advanced stage at diagnosis and poor patient outcomes." (PMID 35784721, 2022). "One such example is vaccination against the mucin 1 (MUC1) antigen in patients at high-risk of colorectal cancer." (PMID 32283684, 2020). "The MUC1 heterodimeric protein is aberrantly overexpressed in colorectal cancer and has been linked to poor outcomes in this disease." (PMID 28153010, 2017). "Mucin 1 (MUC1) is co-expressed with β-catenin at the invasion front of colorectal carcinoma, and is associated with progression of disease and poor prognosis." (PMID 25124875, 2014). "A related Muc-1 vaccine improved survival in a murine model of colitis-associated colorectal cancer, supporting the further testing of preventative cancer vaccination, including utilizing DC, in a prevention setting." (PMID 24379816, 2013). "IgM and IgG anti-MUC1 antibodies have been identified in patients with various adenocarcinomas, and their presence has been associated with better prognosis in breast cancer, colorectal cancer, non-small cell lung cancer, and pancreatic cancer." (PMID 37869082, 2023). "Salicylate inhibits lysine acetyltransferases and MUC1 induces epithelial to mesenchymal transition, which could inhibit colorectal cancer progression since overexpressed MUC1 in colorectal cancer cells is associated with worse prognosis." (PMID 37569878, 2023). "Included within the upregulated genes in the concurrent mutation group were some previously linked with colorectal cancer carcinogenesis, including NFKBIZ, CCL20, LCN2, PLOD2, MUC1, and MUC4." (PMID 40757636, 2025). "Mucin 1 (MUC1) is overexpressed in colorectal cancer (CRC), yet its prognostic value is controversial." (PMID 41332218, 2025). "These novel findings add to MUC1′s potential as a therapeutic target by showing that MUC1 in innate immune cells promotes the development of cancer, at least in colorectal cancer." (PMID 38540735, 2024). "In the experiment of human colorectal cancer cells, anti MUC1 shows potential for colorectal cancer treatment." (PMID 38699634, 2024). "highlighted the central role of MUC1 in colorectal cancer stem cell vaccine immunotherapy, impacting tumor growth and metastasis, particularly notable in enhancing NK cell toxicity and promoting anti-MUC1 antibody generation." (PMID 38361923, 2024). "In this study, we prepared irinotecan hydrochloride (IRI) and capecitabine (CAP)-coloaded liposomes modified by peanut agglutinin (IRI/CAP-PNA-Lips) to target MUC1-positive colorectal cancer." (PMID 35784721, 2022). "The results suggested that PNA-modified liposomes coloaded with IRICAP significantly upregulated the apoptosis in MUC1-positive colorectal cancer cell lines." (PMID 35784721, 2022). "Another MUC1-positive colorectal cancer cell line, SW620, had IC50 values for the IRI/CAP-Lip and IRI/CAP-PNA-Lip groups of 5.4 μg/ml and 4.7 μg/ml, respectively." (PMID 35784721, 2022). "The results showed that IRI/CAP-PNA-Lips showed an enhanced ability to target MUC1-positive colorectal cancer cells compared to unmodified liposomes." (PMID 35784721, 2022). "The results showed that in the MUC1-positive colorectal cancer cell line HT29, the IC50 values for the IRI/CAP-Lip and IRI/CAP-PNA-Lip groups were 5.8 μg/ml and 5.1 μg/ml, respectively." (PMID 35784721, 2022). "In rectal cancer, the sialo-oligosaccharide form of MUC1 has been shown to determine the metastatic potential of colorectal cancer cells and to have clinicopathological utility in evaluating the outcome and prognosis of patients." (PMID 34207342, 2021).
colorectal cancer (continued). "For example, very recent studies highlighted the relevance of MUC1 as an immunogenic protein, specifically overexpressed in colorectal cancer stem cells (CCSC)." (PMID 33498502, 2021). "have reported that the pattern of expression of IgGs against MUC-1 in colorectal cancer differed from that of IgMs." (PMID 29285261, 2017). "MUC1 has very high expression compared to the other mucins in cancerous tissues examined, except for a minor decrease in expression in the colorectal cancers." (PMID 28978023, 2017). "The targeted-MUC1 aptamer conjugated with hyaluronan/chitosan nanoparticles (HACSNPs) was constructed as a vehicle for the targeted delivery of 5-fluorouracil to colorectal cancer cells." (PMID 29872716, 2017). "In colorectal carcinoma, these rates are MUC1, 24–32%; MUC2, 38%; MUC3, 74%; MUC4, 94%; MUC5AC, 34–50%; MUC6, 39%; and MUC16, 64%." (PMID 25551773, 2014). "In appendiceal carcinoma, MUC3, MUC6 and MUC16 had lower expression, MUC2 expression was markedly higher, and MUC1 expression was higher than the respective rates in colorectal carcinoma." (PMID 25551773, 2014). "L-BLP25 targets MUC1 glycoprotein, which is highly expressed in hepatic metastases from colorectal cancer." (PMID 22494623, 2012). "Our data clearly demonstrates a role for MUC1 in the progression of colorectal cancer, probably through its effects on cell adhesion and metastasis." (PMID 17349047, 2007). "MUC1 expression in colorectal cancer is an independent marker of poor prognosis, even when vascular invasion is included in the analysis." (PMID 17349047, 2007). "MUC1 expression appears to function as an independent prognostic marker in colorectal cancer even when the conventional variables of tumour stage and vascular invasion status are included in the analysis." (PMID 17349047, 2007). "Our data confirm that high expression of MUC1 in colorectal cancer confers a worse prognosis both on univariate and multivariate analysis, even when taking into account the potentially confounding influence of vascular invasion status." (PMID 17349047, 2007). "According to our study, patients with early-stage colorectal cancer (T1-T2) as well as patients with very early-stage colorectal cancer (Tis-T1) had higher total numbers of MVs, EMVs, MUC-1-positive MVs, TF-positive MVs, EMV/TF combined MVs, and MUC-1/TF combined MVs compared to controls." (PMID 38792021, 2024). "Among these targets, MUC1 was characterized as a stemness driver in colorectal cancer where MUC1 forms a complex with MYC transcriptional factor and activates the expression of leucine-rich repeat-containing G protein-coupled receptor 5 (LGR5) gene, a marker of the intestine stem cells and CSCs." (PMID 36900399, 2023). "Mucin 1 (Muc1) has been mostly studied in colorectal cancer." (PMID 35053365, 2022). "The authors identified hepatocyte nuclear factor 4α (HNF4A), mutated in colorectal cancer (MCC) and mucin 1 (MUC1) as central network regulators which, together with miR-545-3p and miR-519c-3p, distinguished COPD exacerbations from community acquired pneumonia." (PMID 35820851, 2022). "This also suggests that the C‐terminal part of MUC1 could be a key transcription factor to control the “stemness” of hMSCs in the hypoxic niche of bone marrow as shown in colorectal cancer." (PMID 34687046, 2022). "Mucin 1 (MUC1) is a type of tumor-associated carbon antigen (TACA), which is a highly glycosylated mucin, and studies have shown that it is an important biomarker in colorectal cancer." (PMID 35784721, 2022).
colorectal cancer (continued). "PANVACTM has been shown to enhance CEA and MUC1-specific cytotoxic T-lymphocyte response in preclinical models and has already been tested in diverse tumor entities including pancreatic and colorectal cancer." (PMID 35158964, 2022). "Therefore, PNA-modified liposomes can actively target MUC1-positive colorectal cancers to deliver drugs centrally." (PMID 35784721, 2022). "MUC1 is a glycoprotein and tumor-associated antigen (TAA) for colorectal cancer." (PMID 33869008, 2021). "The protein expression of MUC1 might be a poor biomarker in colorectal cancer and might play a role in tumor transformation and metastasis." (PMID 31933627, 2019). "Research on MUC1 as a target in colorectal cancer has been focused on the development of a vaccine." (PMID 28153010, 2017). "MUC1 is known to be overexpressed in human colorectal cancer cells." (PMID 28153010, 2017). "Moreover, GO-203 inhibits MUC1 positive colorectal cancer cell proliferation by decreasing intracellular GSH levels and enhanced ROS production." (PMID 28153010, 2017). "CRC is reported to have MUC1 expression in ~61% of pT1, 78% of pT2, 98% of pT3 and 90% of pT4 colorectal cancer samples and thus clearly correlates with invasiveness, being an optimal target for MUC1 based vaccination strategies after resection of hepatic metastases." (PMID 22494623, 2012). "MUC1 was previously shown to mediate a pro-apoptotic response in hamster ovary cells and it was also attributed with anti-apoptotic functions in myeloma, breast and colorectal carcinoma cell lines." (PMID 22073229, 2011). "MUC1 is a membrane bound glycoprotein which has been demonstrated to be predictive of tumour progression and worsening prognosis in both gastric and colorectal cancer including those related to HNPCC." (PMID 17349047, 2007). "Furthermore, MUC1 could contribute to the tumour growth-promoting role of mucus and serve as an independent indicator of poor survival in colorectal cancer." (PMID 39966658, 2025). "Therefore, it is plausible to hypothesize that a similar pathway involving MUC1 may be involved in the development of colorectal cancer." (PMID 38699634, 2024). "Thus, using MUC1-specific ligands to modify liposomes could enable targeted delivery of drugs to MUC1-positive colorectal cancer tissue." (PMID 35784721, 2022). "Moreover, staining of the KL-6 antibody that reacts with sialylated MUC1 has been observed in colorectal cancer suggesting the possibility that MUC1-ST could be present in colorectal cancer." (PMID 33149188, 2020). "In addition, MUC1 expression was found in 100% (56/56) of colorectal cancer liver metastases." (PMID 22494623, 2012). "One notable strategy employed the MUC1-specific 5TR1 aptamer conjugated to DOX-loaded liposomes (PLD), which showed superior antitumor efficacy in murine colorectal cancer models." (PMID 41560835, 2026). "Beyond MUC1 and EpCAM, the nucleolin-binding aptamer AS1411 has also been extensively applied in colorectal cancer nanomedicine." (PMID 41560835, 2026). "NCT02839954 is a phase 1/2 trial investigating the safety and efficacy of anti-MUC1 CAR-NK cells in patients with relapsed or refractory solid tumors, including GBM, HCC, breast, pancreatic, gastric, and colorectal cancer expressing MUC1." (PMID 37371075, 2023). "For proof-of-principle, we used antibody-targeted molecular imaging of colorectal cancer (CRC) in a mouse model, expressing human MUC1 at tumor sites." (PMID 35328163, 2022). "Other studies have shown MUC1, and MUC4 have been to promote nuclear localization of β-catenin in gastrointestinal and colorectal cancers." (PMID 35255004, 2022).